CSF1R (colony stimulating factor 1 receptor)
Diseases named in the same sentence as CSF1R in open-access papers (continued):
Sharing a sentence is not in itself a finding about the gene and the disease.
infection (continued). "In accordance with our experiments, CSF1R-mediated microglia depletion experiments during neuroinvasive WNV infection resulted in diminished local restimulation of CD8+ T cells within the brain and enhanced susceptibility to infection." (PMID 40619428, 2025). "Interestingly, in vaccinated fish, the detection of csf1r (FC of 0.58), related to macrophages and inflammatory process, was also detected but early on in the infection (24 hours pi)." (PMID 37346045, 2023). "Western blot analyses revealed that lenti-shHMGB1 infection remarkably decreased HMGB1 expression which resulted in significant upregulation of mRNA level of the macrophage-like differentiation markers (CD14, CD11b, and CSF1R) as compared with the lenti-ctrl infection." (PMID 33128580, 2021). "We also investigated whether CSF1R signaling was necessary for the antiviral response during sustained TMEV infection by initiating PLX5622 treatment at the chronic stage of infection." (PMID 34566948, 2021). "Given the central role of macrophages in fighting infection, long-term blockade of the CSF1R/CSF-1/IL-34 axes could compromise the response to infection." (PMID 32581720, 2020). "In a model of MHV infection, depletion of microglia using colony-stimulating factor 1 receptor (CSF1R) inhibitors revealed that depletion of microglia at 0–6 days of infection would result in increased mortality and a later depletion had no influences on survival." (PMID 30967139, 2019). "Microglial depletion via CSF1R inactivation improves cognition in mouse models of neuroinflammation, but limits virologic control in the CNS of mouse models of neurotropic infections by unknown mechanisms." (PMID 30704498, 2019). "Moreover, the expression of CSF1R (macrophage colony-stimulating factor 1 receptor) was higher in uninfected kittens compared to uninfected adults, and steadily increased over the GI.1 infection time-points, but remained stable in GI.2-infected kittens." (PMID 30235853, 2018). "Western blot analysis revealed that lenti-shZFP36L1 infection remarkably decreased ZFP36L1 expression which resulted in significant down-regulation of the mRNA levels of the monocyte/macrophage differentiation markers (CD11B, CD14 and CSF1R) as compared with the lenti-control (lenti-ctrl) infection." (PMID 26542173, 2015). "To test this hypothesis and directly observe the dynamic changes of CRICs in response to P. aeruginosa infection, we performed P. aeruginosa (19660; ATCC) infection in the cornea of ko and wt control mice on the Csf1r-EGFP background and harvested them at 3 and 6 hpi for confocal microscopy." (PMID 33208381, 2020). "The perivascular aggregation of CSF1R-transgene+ cells in the air sac could indicate that these cells play an important role in the induction of the local immune response as previously seen after infection with IBV and E. coli." (PMID 30305141, 2018). "K18-hACE2 mice were fed pre-formulated chow containing either the CSF1R inhibitor PLX5622 (1,200 ppm) or control chow 7 days prior to intranasal infection with 5 × 104 PFU of SARS-CoV-2, and remained on drug for the duration of the experiment." (PMID 34935438, 2022). "The other CSF1R‐related ALSP patient (proband 3) received allogeneic stem cell transplantation and died of graft‐versus‐host disease and uncontrolled infection 15 days after the transplantation." (PMID 31885218, 2020). "In contrast to in vivo data, APEC O2-GFP was more invasive in CSF1R-tghigh cells in vitro than APEC O1-GFP and had higher survival rates for up to 6 h post-infection." (PMID 31998322, 2019). "CSF1R mRNA and HIF-1α target gene expression were up-regulated in the skin and down-regulated in the intestine post infection." (PMID 28542591, 2017). "Many up-regulated genes are closely related to inflammation and immune responses, such as CCL20, IL6, CXCL1, CSF1R, CCR5, TNFRSF8, indicating that mice infected N. farcinica via these two infection routes may lead to robust inflammatory response." (PMID 40723822, 2025).
infection (continued). "Moreover, APEC O2-GFP exhibited greater invasions in CSF1R-tghigh cells in vitro than APEC O1-GFP, with higher survival rates observed for up to 6 h post-infection." (PMID 39203441, 2024). "Similar to mice lacking CSF-1, a ligand for CSF-1R, they succumbed to infection earlier than wild-type siblings." (PMID 26159717, 2015). "The colonization of embryonic tissues by macrophages was shown to be dependent on the macrophage colony-stimulating receptor (Fms/Csf1r), but this receptor is not involved in the recruitment of macrophages to sites of infection." (PMID 21366518, 2011). "In our experimental model, elimination of microglia by CSF1R blockade was highly selective, as it did not have a significant impact on circulating and splenic leukocytes (including myeloid cell types), and infection-induced increases in circulating granulocytes was preserved in PLX5622-treated mice." (PMID 30027450, 2018). "Furthermore, the ability of Csf1r-Cre+Axlfl/fl infected mice to mount protective adaptive antiviral responses is consistent with the preserved expression of AXL in lung DCs and the lack of increased susceptibility to infection in this conditional knock out line." (PMID 27350258, 2016).
neurodegenerative disease (55 papers, 2015 to 2026). A disorder of the central nervous system characterized by gradual and progressive loss of neural tissue and neurologic function. "Some diseases are specifically caused by gene mutations occurring solely within microglia, such as colony-stimulating factor 1 receptor (CSF-1R) mutation-induced neurodegenerative diseases." (PMID 39300451, 2024). "Several studies have shown that dysregulation of the Csf1r gene and its associated signaling pathway is linked to microglial dysfunction and, in turn, the pathogenesis of neurodegenerative diseases." (PMID 37410787, 2023). "Several studies have highlighted the role of pathogenic mutations in CSF1R originate in microglia contributing to other neurodegenerative diseases, including FTD." (PMID 34867307, 2021). "Given that CSF1R is expressed in a wide range of myeloid cells, altered CSF1R signaling is implicated in inflammatory, neoplastic, and neurodegenerative diseases." (PMID 32801364, 2020). "Future prospective studies involving different potential confounding factors in populations of different ethnicities are merited to confirm the potential association between CSF1/CSF1R signaling and PD or other neurodegenerative diseases." (PMID 31554150, 2019). "Given the high genetic overlap between different neurodegenerative diseases, further studies to assess the association between more genetic variants of CSF1R and PD or other neurodegenerative diseases are warranted." (PMID 31554150, 2019). "CSF1R mutations are part of a small but growing list of microglia-associated neurodegenerative diseases." (PMID 25935893, 2016). "CSF1R mutations have been linked with many neurodegenerative diseases." (PMID 40949796, 2025). "Genetic variations of the CSF1R gene have been implicated in several neurodegenerative diseases." (PMID 40949796, 2025). "The results revealed that compared with the control group, the apoptotic proteins p-CSF-1R/CSF-1R, p-Nrf2/Nrf2, and Bcl-2/Bax, associated with neuronal injury and degenerative diseases, were significantly decreased, and cleaved caspase-3 expression was significantly increased." (PMID 40278547, 2025). "In this sense, deficiencies in key genes for microglial survival and/or proliferation (such as CSF1R or TREM2) are associated with rare hereditary neurodegenerative diseases, such as adult-onset leukoencephalopathy with axonal spheroids or Nasu–Hakola disease (respectively)." (PMID 27743026, 2016). "In summary, CSF1R inhibitors represent a promising therapeutic approach for treating neurodegenerative diseases." (PMID 40153574, 2025). "CSF1R inhibitors offer a promising therapeutic strategy for neurodegenerative diseases by reducing microglial populations and the parallel neuroinflammation." (PMID 36771351, 2023). "Colony-stimulating factor-1 receptor (CSF-1R)-related leukoencephalopathy (CRL) is a neurodegenerative disease that triggers early demyelination, leading to an adult-onset dementia." (PMID 37626591, 2023). "Microglial viability and proliferation depend on signaling through the CSF1R, the expression of which is significantly increased in neurodegenerative diseases." (PMID 37332353, 2023). "CSF1R inhibitors were shown to be protective in mouse models of other neurodegenerative diseases, such as AD and Down syndrome." (PMID 36624100, 2023). "Cumulative findings have indicated that CSF-1R inhibitors can have beneficial effects in preclinical neurodegenerative disease models." (PMID 35366105, 2022). "Mutations in the CSF1R gene are the most common cause of adult-onset leukoencephalopathy with axonal spheroids and pigmented glia (ALSP), a neurodegenerative disease with rapid progression and ominous prognosis." (PMID 36559271, 2022). "Colony stimulating factor 1-receptor (CSF-1R) is predominantly expressed on microglia and its expression is significantly increased in neurodegenerative diseases." (PMID 35366105, 2022).
neurodegenerative disease (continued). "As our understanding is rapidly evolving, we herein focus on the most updated preclinical and clinical evidence regarding potential microglia-based therapy in neurodegenerative diseases through targeting of the colony stimulating factor-1 receptor (CSF-1R)." (PMID 35366105, 2022). "Abnormal CSF-1R expression is thought to interfere with microglia functioning and contribute to neurodevelopmental disorders and neurodegenerative diseases." (PMID 34838047, 2021). "In neurodegenerative disease, CSF1R signaling activates proinflammatory processes through the regulation of CSF1 and IL-34 signaling." (PMID 33192177, 2020). "AARS2‐related ALSP is an autosomal recessive neurodegenerative disease while CSF1R‐related ALSP is inherited in a dominant manner." (PMID 31885218, 2020). "Colony stimulating factor 1 receptor (CSF1R) is critically involved in regulating microglial proliferation, and CSF1R blocking strategies have been recently used to modulate microglia in neurodegenerative diseases." (PMID 33162994, 2020). "We showed that JNJ-527 is a CNS-penetrant CSF1R inhibitor and established an optimal dose for preclinical applications, and estimate an efficacious dose for further clinical investigations in neurodegenerative disease." (PMID 31504240, 2019). "Colony stimulating factor 1 receptor inhibition was also tested in models for neurodegenerative disease to limit damaging neuroinflammation at disease end stage." (PMID 29681904, 2018). "Activation of the CSF-1R/PLCγ2/ERK/Nrf2 pathway may be associated with inflammatory and neurodegenerative diseases." (PMID 40278547, 2025). "In addition, CSF1R protein was shown to play a role in other neurodegenerative diseases, and its inhibitors showed promising results in preclinical studies." (PMID 37349768, 2023). "In addition, inhibition of CSF-1R has been proposed as a potential therapeutic strategy for neurodegenerative diseases, including AD." (PMID 37410787, 2023). "Moreover, CSF1R is known to play a key role in neurodegenerative diseases, including AD; expression of CSF1R was enhanced in microglia near β–amyloid plaques in transgenic mice and was upregulated in postmortem brain tissues of AD patients." (PMID 35337075, 2022). "While CSF1R inhibition is a well accepted approach to assess the role of microglia in neurodegenerative diseases, potential side-effects must be considered, as well as potential contributing roles of perivascular and meningeal macrophages, which are also eliminated." (PMID 34103079, 2021). "Although these studies were the first to identify a neuropathogenic effect associated with elevated CSF-1R signaling, future investigations may reveal pathological consequences related to increased CSF-1R signaling in other neurodegenerative diseases." (PMID 34838047, 2021). "Nonetheless, taken together, these studies indicate that aberrant PI3K-AKT signaling due to abnormal CSF-1R expression is detrimental to brain development, and may promote the onset of neurodegenerative diseases." (PMID 34838047, 2021). "In neurodegenerative disease, CSF1R signaling might activate proinflammatory processes through regulating CSF1 and IL34 signaling." (PMID 32908485, 2020). "Recent data pinpoint that mutations in triggering receptor expressed on myeloid cells 2 (Trem2) and colony stimulating factor 1 receptor (Csf1r) in microglia are responsible of neurodegenerative diseases, reinforcing the essential role of microglia in healthy aging." (PMID 32121189, 2020). "CSF1R inhibitors are widely used to study the role of microglia in several diseases including neurodegenerative disease as AD, and we and others previously showed that four weeks of treatment with the CSF1R inhibitor PLX5622 depleted microglia in WT and APP-PS1 mice." (PMID 32771067, 2020).
neurodegenerative disease (continued). "We identified 70 additional novel and missense variants in other genes, such as MAPT, GRN, CSF1R, and PRNP, related to neurodegenerative diseases, which may represent overlapping clinical and neuropathological features with AD." (PMID 31182772, 2019). "Similarly, Green and colleagues have shown the effectiveness of CSF1R inhibition in neurodegenerative disease models suggesting that CSF1R inhibition was equally effective in other brain injury scenarios." (PMID 31753024, 2019). "Hence, differentially alter the role of CSF1R-mediated microglial activation during neurodegenerative disease progression may provide a unique opportunity for more suitable and effective therapeutics." (PMID 34867307, 2021). "CSF1R inhibition may have therapeutic potential in tau-mediated neurodegenerative diseases." (PMID 31504240, 2019). "SS + RSD mice show enrichment for genes related to neurodegenerative disease processes (CTNNB1, CSF1R, VCP), while sirtuins, which prevent aging and neurocognitive diseases, were less enriched." (PMID 39629138, 2024). "Inhibition of Colony-stimulating factor 1 receptor (CSF1R), a receptor involved in microglial survival and proliferation, has been shown to reduce microglial activation and neuroinflammation in various neurodegenerative diseases." (PMID 41221080, 2025). "Accordingly, we can hypothesize the following: 1) changes in metabolites over time could facilitate an understanding of the metabolism of this rare neurodegenerative disease, and 2) MRS could help to screen pedigrees and thus detect asymptomatic members who carry CSF1R abnormalities." (PMID 28025469, 2017). "As prolonged near-complete microglial elimination, which is achieved with the higher doses of CSF1R inhibitors, may not be translatable for the full duration of a neurodegenerative disease, lower levels of CSF1R inhibitors may offer a chronic option for the treatment of neuroinflammation." (PMID 26232154, 2015). "There are no studies on quality of life (QoL) in CSF1R-ALSP; however, in other neurodegenerative diseases, cognition was shown to be one of the most important determinants of the QoL of patients and their caregivers." (PMID 36559271, 2022).
neurological disorders (29 papers, 2016 to 2025). "In-vitro autoradiography and binding assays using [3H]CPPC revealed its limited ability to detect CSF1R associated with neurological disorders." (PMID 40166008, 2025). "Further research should delve into the specific roles of associated molecules, such as CSF1 and CSF1R, in neurological diseases." (PMID 39113712, 2024). "Toxic effects are dependent on the status of underlying neurologic disease, largely prevented by the CSF1R inhibitor pexidartinib, and influenced by oxygen concentration in the carrier gas." (PMID 37770252, 2023). "Given that AARS2 is responsible for the translation of mitochondrial proteins and that mitochondria dysfunction is essential in the pathogenesis of neurological diseases such as AD, it is possible that both CSF1R and AARS2 deficiency affects the mitochondrial structural and functional integrity." (PMID 34867307, 2021). "Our study confirms previous findings that CSF1R mutations are a relatively common cause of adult onset leukodystrophy and that CSF1R mutations can lead to diverse phenotypes and can mimic many other neurological diseases, including CNS vasculitis." (PMID 25935893, 2016). "The spectrum of neurological diseases associated with CSF1R variants has substantially increased in recent years and is still ongoing, which calls for in-depth mechanistic investigations on CSF1R’s diverse roles in these diseases at the different disease stages." (PMID 34867307, 2021). "Triggering receptor expressed on myeloid cells-2 (TREM2) and colony-stimulating factor 1 receptor (CSF1R) are crucial molecules for microgliopathy, which is characterized by microglia dysfunction and has recently been proposed as the neuropathological hallmark of neurological disorders." (PMID 33841415, 2021). "Thus, TREM2 and CSF1R are considered crucial molecules for “microgliopathy”, which is characterized by reactive gliosis and microglia dysfunction and has been recently proposed as the neuropathological hallmark of neurological disorders." (PMID 33841415, 2021). "Considering that the survival and proliferation of microglia and macrophages rely on the CSF1R signaling pathway, several CSF1R inhibitors have been developed as potential therapies for neurological disorders and cancer." (PMID 40166008, 2025). "The comparison thus supports evidence generation for the role of CSF-1R across neurological diseases." (PMID 34950148, 2021). "Understanding the pathophysiology of CSF1R is critical for developing targeted therapies for related neurological diseases." (PMID 34867307, 2021). "The expression levels of CSF1 and CSF1R on neurons were significantly upregulated after various neurological diseases." (PMID 33101590, 2020). "Recent studies showed that the activation of CSF1R with CSF1 exerted anti-inflammatory effects in a variety of nervous system diseases." (PMID 32522286, 2020). "As CSF1 regulates differentiation, maintenance and proliferation of myeloid lineage cells several pharmacological agents inhibiting CSF1R had been tested in animal models of neurological disorders." (PMID 30386212, 2018). "In addition, peripheral CSF1 levels correlate with CSF1R levels in CNS, and peripheral administration of CSF1R ligands ameliorates neurological disorders." (PMID 36969154, 2023). "Indeed, recent studies have demonstrated the importance of CSF-1R signaling in microglial and neural development and function in which CSF-1R activations resulted in pleotropic protective effects in multiple neurological diseases." (PMID 32522286, 2020). "Therefore, further studies on CSF1R-related disorders may lead to a better understanding of these disorders and pave the way toward curative therapy in other neurological disorders." (PMID 37349768, 2023). "Given the lack of effective diagnostic criteria for CSF1R associated neurological diseases, the soluble form of CSF1R may be a promising biomarker and therapeutic target for CSF1R-associated neurodegenerative disorders." (PMID 34867307, 2021).